BRAF (B-Raf proto-oncogene, serine/threonine kinase)
Diseases named in the same sentence as BRAF in open-access papers (continued):
Sharing a sentence is not in itself a finding about the gene and the disease.
metastatic melanoma (continued). "The BRIM 3 study, a phase III randomized clinical trial, compared vemurafenib with dacarbazine in 675 patients with previously untreated, metastatic melanoma with BRAF mutation." (PMID 23420786, 2013). "Vemurafenib (ZelborafTM, Roche Pharmaceuticals Ltd, Sydney, Australia), is a serine-threonine kinase BRAF inhibitor that has demonstrated efficacy in treating metastatic or unresectable metastatic melanoma that has a known mutation in BRAF protein." (PMID 24314265, 2013). "The BRAF inhibitor, vemurafenib, has recently been approved for the treatment of metastatic melanoma in patients harboring BRAFV600 mutations." (PMID 22651703, 2012). "Improved survival was also reported for treatment of metastatic melanoma patients carrying a specific BRAF mutation (∼40% of all melanoma patients) using the highly selective V600E kinase inhibitor vemurafenib." (PMID 22719881, 2012). "The pivotal phase III trial was run in a selected patient population of 675 patients with previously untreated, metastatic melanoma with the BRAF V600E mutation and showing a tremendous clinical benefit over chemotherapy." (PMID 25562363, 2012). "Mutation of BRAF is detected in all stages of melanocytic lesions including nevi, primary and metastatic melanoma." (PMID 23056577, 2012). "In patients with metastatic melanoma featuring BRAF V600E mutation, phase 1 and 2 clinical trials of the BRAF kinase inhibitor vemurafenib (PLX4032) have shown response rates of more than 50%." (PMID 22846499, 2012). "In vitro, we showed that ABCB5-expressing cells selectively survive when exposed to dacarbazine, the reference treatment of metastatic melanoma, but also to vemurafenib, a new inhibitor of the mutated kinase V600E BRAF and other various chemotherapeutic drugs." (PMID 22675422, 2012). "For patients with BRAF-mutation positive metastatic melanoma, vemurafenib and ipilimumab both represent important approved treatment options." (PMID 22640478, 2012). "Vemurafenib has been approved by the US Food and Drug Administration (FDA) for the treatment of patients with unresectable or metastatic melanoma carrying the BRAF (V600E) mutation." (PMID 23085539, 2012). "In metastatic melanoma patients, about 45% of their cancer expresses a specific mutation, V600, in an intracellular signaling kinase, BRAF." (PMID 29147288, 2012). "Recently, vemurafenib, a potent inhibitor of mutated BRAF, has demonstrated a survival benefit in metastatic melanoma with BRAFV600E mutation." (PMID 22870241, 2012). "Targeting just a few out of several potential mutations, BRAF-Inhibitors such as PLX 4032 achieved already tremendous results in the therapy of metastatic melanoma." (PMID 22007305, 2011). "In contrast, the presence of a BRAF mutation in metastatic melanoma is associated with a poorer survival from time of first metastasis or time from first resected metastasis, although not consistently observed in smaller studies." (PMID 21139585, 2011). "Basal NFAT transcriptional activity was measured in three human metastatic melanoma cell lines with different BRAF mutational status." (PMID 19724275, 2009). "In particular, human metastatic melanoma WM9 cells have a constitutively active ERK1/2 MAPK pathway most likely due to the V600E BRAF mutation found in these cells." (PMID 19919690, 2009). "We previously reported an analysis of BRAF mutations in metastatic melanoma samples from 68 patients." (PMID 15613230, 2004). "We have reported the analysis of BRAF mutations in a cohort of metastatic melanoma patients and noted a mutation proportion of 44%." (PMID 15613230, 2004). "In summary, this analysis represents the largest study to date correlating BRAF mutations and clinical outcomes in metastatic melanoma." (PMID 15613230, 2004).
metastatic melanoma (continued). "Vemurafenib is a selective BRAF inhibitor that prevents the growth of cancer cells by inhibiting the activity of BRAF mutant proteins, and is approved for the treatment of unresectable or metastatic melanoma bearing the V600E mutation of BRAF." (PMID 41592028, 2026). "Our findings suggest that specific gut microbial taxa and immune-related gene expression patterns may be associated with differential responses to BRAF/MEK-targeted therapy in metastatic melanoma." (PMID 40659866, 2025). "Moreover, patients with BRAF V600-mutated metastatic melanoma who received triple combination therapy targeting BRAF, ERK, and PD-1 exhibited a durable antitumor response." (PMID 40075727, 2025). "As many as 50 % of metastatic melanomas harbor BRAF point mutations, including BRAF V600E." (PMID 40977811, 2025). "In addition, mOS tended to be longer in the post-approval era than the pre-approval era for advanced/metastatic melanoma patients with BRAF mutations and high-risk advanced RCC patients." (PMID 40831930, 2025). "Additionally, dabrafenib (GSK2118436), designed for mutated BRAFs, and trametinib, a specific MEK 1/2 inhibitor, gained FDA approval in 2013 as individual treatments for metastatic melanoma with BRAF mutations." (PMID 39582535, 2024). "Vemurafenib is a BRAF inhibitor that is typically used to treat metastatic melanoma; however, this molecular mechanism can trigger RAS mutations due to a paradoxical activation of mitogen-activated protein kinase (MAPK), which can lead to the development of cSCC." (PMID 38795220, 2024). "It is worth noting that BRAF mutations have been identified in 50–60% of all metastatic melanomas, with about 80–90% of these mutations involving the substitution of valine for glutamine at amino acid 600 (V600E), which is associated with a poor overall prognosis." (PMID 38594618, 2024). "This was a retrospective study assessing the clinical activity, outcomes, and potential clinical factors associated with survival among patients with BRAFV600-mutated metastatic melanoma treated with BRAF/MEKi after disease progression on immune checkpoint inhibition." (PMID 37971411, 2024). "This compares to an mPFS of 16.8 m (anti-PD-1/CTLA-4), 5.6 m (anti-PD-1), and 3.4 m (anti-CTLA-4) in CHECKMATE-067, and 11.6 m (Anti-PD-1) in KEYNOTE 006, both trials of ICIs in metastatic melanoma, with a pre-specified stratification for patients with BRAF mutations." (PMID 38339280, 2024). "Trametinib is a highly selective reversible allosteric inhibitor of MEK1/2 activity, approved in the treatment of cancers with the activation of the RAS/MAPK pathway, such as BRAF V600E mutated metastatic melanoma and BRAF V600E mutated non-small-cell lung cancer." (PMID 39594917, 2024). "Furthermore, in a multicenter study involving metastatic melanoma patients with well-defined BRAF mutations, 856 individuals were selected to analyze BRAF mutation patterns, their response to MAPK pathway inhibitors, and survival outcomes." (PMID 39582535, 2024). "The CPM #10 covering almost the entire skin cancer cell lines included the pharmaceutical agent PLX4720 (vemurafenib) and BRAF mutation; the efficacy of vemurafenib has been tested in several clinical trials for treating unresectable or metastatic melanoma with BRAF V600E mutation." (PMID 38974382, 2024). "Furthermore, vemurafenib, the first BRAF inhibitor approved by the FDA in 2011 for metastatic melanoma with the BRAFV600E mutation, has demonstrated an increase in OS compared with dacarbazine in a phase III (BRIM-3) trial." (PMID 38474231, 2024). "BRAF mutations are present in approximately 50% of the patients with metastatic melanoma." (PMID 39336897, 2024). "An observational study evaluated more than 1000 patients with metastatic melanoma with BRAF V600 mutation and treated in the first line with either BRAFi/MEKi or ICIs (PD-1 single agent or combined PD-1/CTLA-4 antibodies), included in the EUMelaReg treatment registry." (PMID 36995534, 2023).
metastatic melanoma (continued). "To investigate whether BRAF protein mutations affect the RIPK4 expression level in metastatic melanoma, we analyzed clinical samples." (PMID 36765875, 2023). "Our study found the BRAF V600E mutation in six cases among 43 metastatic melanomas." (PMID 37649946, 2023). "On December 22, 2014, the FDA granted accelerated approval to nivolumab (OPDIVO; Bristol-Myers Squibb, New York, NY) for the treatment of patients with unresectable or metastatic melanoma and disease progression following ipilimumab and, if BRAF V600 mutation is positive, a BRAF inhibitor." (PMID 37366435, 2023). "In December of 2014, the FDA granted approval for Nivolumab, commercially known as Opdivo, for the treatment of metastatic melanoma in patients who had previously been treated with Ipilimumab and also for those who had become BRAF V600 mutation positive after treatment with a BRAF inhibitor." (PMID 37605149, 2023). "Additionally, it was later approved for use in combination with BRAF inhibitors and has become a mainstay for the treatment of patients with unresectable or metastatic melanoma with BRAF mutations." (PMID 37235843, 2023). "Around half of all metastatic melanoma cases harbor BRAF mutations, particularly, valine (V) for glutamic acid (E) substitution at position 600 (V600E), which accounts for roughly 84.6 percent of all BRAF mutations." (PMID 36649046, 2023). "Similarly, a small study of 16 patients with BRAF-mutated metastatic melanoma treated with vemurafenib/ipilimumab combination therapy who underwent 18F-FDG-PET/CT detected 7 patients developing at least one irAE (most frequently colitis and arthritis)." (PMID 36911692, 2023). "In conclusion, by dividing patients with BRAF-mutated metastatic melanoma into three prognostic categories based on the baseline assessment of ECOG PS, LDH, and metastatic sites, we noted a different activity and efficacy of both targeted therapies and AntiPD1 monotherapy." (PMID 36046043, 2022). "We also found that BRAF class 1 mutations (20.3% vs. 5.8%) were more frequent in metastatic melanomas, while SPRED1 inactivation (3.9% vs. 19.8%), SF3B1 mutations (1.6% vs. 9.3%), and amplifications of CRKL (6.3% vs. 17.4%) and MAPK1 (1.6% vs. 11.6%) were more frequent in primary samples." (PMID 35706047, 2022). "A combination of a BRAF and a MEK inhibitor (BRAFi/MEKi-combined targeted therapy) has revolutionized the management of metastatic melanoma patients harboring a BRAF mutation at codon 600, significantly improving their overall survival (OS) and progression-free survival (PFS)." (PMID 36077693, 2022). "While for some drugs the variation in drug response can be explained by a very specific mutation (for instance, BRAF V600E mutation is a strong predictor for response to Vemurafenib in metastatic melanoma), for many drugs the knowledge of the mechanism of action is missing." (PMID 36428696, 2022). "MEK inhibitors approved (in combination with a BRAF inhibitor) for therapy of metastatic melanoma with a BRAF V600E or V600K mutation are trametinib (in combination with dabrafenib), cobimetinib (in combination with vemurafenib), and binimetinib (in combination with encorafenib) [3••–4••, 9••]." (PMID 35380338, 2022). "However, it is currently FDA-approved for unresectable or metastatic melanoma with the BRAF V600E mutation as detected by an FDA-approved test." (PMID 36172151, 2022). "Although of interest, this study was focused on B16F10 mouse metastatic melanoma cell line, wild-type respect to either BRAF or NRAS mutations, and indicated the tumor microenvironment as key mediator of LY500307 effects, without evidence of any cell-dependent pathway activation." (PMID 35371312, 2022).
metastatic melanoma (continued). "The treatment of melanoma cells with the NAMPT inhibitor FK866 caused the production of ROS, blocked cancer cells at G2/M phase, leading to cell apoptosis, and improved mouse survival in a xenograft model, demonstrating that NAMPT is a therapeutic target in metastatic melanoma with BRAF mutation." (PMID 35565188, 2022). "BRAF mutation occurs in more than 66% of cases of metastatic melanoma." (PMID 35332658, 2022). "Our group is currently trying to define the role that gut microbiota may have in the outcome of metastatic melanoma BRAF-mutated patients treated with BRAF/MEKi." (PMID 36233289, 2022). "Both, MEK inhibitors and PPARγ agonists are used in a novel function compared to the common ways of application, namely for efficacious targeted control of BRAF mutated metastatic melanoma in combination with BRAF inhibitors or for overcoming insulin resistance, respectively." (PMID 35814409, 2022). "A mutation in the kinase BRAF is observed in more than 66% of metastatic melanoma cases." (PMID 35332658, 2022). "BRAF V600 mutation-positive unresectable or metastatic melanoma." (PMID 35037899, 2022). "The purpose of the present study was to assess the safety and tolerability of BRAFi and BRAFi-based combination therapies [MEK inhibitors (MEKi) or anti-programmed death-1 (PD-1) antibody] in Chinese patients with BRAF V600E/K mutation-positive metastatic melanoma." (PMID 33868987, 2021). "Early phase I and II single arm trials suggested that anti-PD-1 plus BRAF inhibitor and MEK inhibitor may be associated with a higher percentage of patients with BRAF V600-mutant metastatic melanoma achieving more durable responses." (PMID 33827575, 2021). "Several inhibitors targeting BRAF and MEK have been deployed in patients with metastatic NSCLC harboring BRAF V600E mutations, patients with unresectable or metastatic melanoma harboring BRAF V600E/K mutations and patients diagnosed with anaplastic thyroid cancer carrying BRAF V600E mutations." (PMID 33467099, 2021). "Squamoproliferative lesions such as actinic keratoses and CSCC are most commonly seen with BRAF inhibitors such as vemurafenib, dabrafenib, and encorafenib, which can be used as monotherapies for patients with metastatic melanoma harboring BRAF V600E mutations." (PMID 34830796, 2021). "Finally, Palbociclib and Vemurafenib were tested in an open-label Phase I-II trial involving patients with stage IIIC or IV BRAF-V600E/K mutant metastatic melanoma harboring CDKN2A loss and wild type-RB1-expression." (PMID 34071228, 2021). "Notably, FDA has approved atezolizumab for unresectable or metastatic melanoma harboring BRAF mutation in combinatorial regimens with targeted therapies." (PMID 34924562, 2021). "There is no toxicity accumulation in long-term treatment, but it was reported that cobimetinib caused blurred vision and eye photophobia in the treatment of metastatic melanoma with BRAF mutations, and the symptoms were basically resolved 14 days after treatment." (PMID 34976824, 2021). "Using a threshold of $33,357 per QALY, dabrafenib in combination with trametinib is a very cost-effective treatment option compared with vemurafenib for previously untreated patients with BRAF V600 mutation-positive unresectable or metastatic melanoma in China." (PMID 34201096, 2021). "Nearly half of patients with advanced and metastatic melanomas harbor a BRAF mutation." (PMID 33406789, 2021). "Clinical data and treatment patterns were retrospectively collected from all patients treated for newly diagnosed locally advanced or metastatic melanoma between May 2014 and December 2017 with available BRAF mutation status and receiving systemic therapy." (PMID 34503304, 2021). "Thus, the purpose of this study was to analyze the safety and tolerability of BRAFi and BRAFi-based combination therapy (MEKi or anti-PD-1 antibody) in Chinese patients with BRAF V600E/K mutation-positive metastatic melanoma." (PMID 33868987, 2021).
metastatic melanoma (continued). "A partitioned survival model was developed to evaluate the cost-effectiveness of dabrafenib plus trametinib versus vemurafenib as a first-line treatment for patients with BRAF V600 mutation-positive unresectable or metastatic melanoma from a Chinese healthcare system perspective." (PMID 34201096, 2021). "In conclusion, our results showed that PLA1A might be a promising diagnostic marker in patients with advanced metastatic melanoma, providing a more accurate diagnostic marker for BRAF-mutant samples of MM patients." (PMID 33723350, 2021). "The BREAK-MB study enrolled 172 patients with BRAF V600 mutated metastatic melanoma." (PMID 32575838, 2020). "This molecule is an oral BRAF inhibitor selective for BRAFV600E that was approved by the FDA in June 2018 for use in combination with the MEK inhibitor binimetinib (MEK162) in treating metastatic melanoma patients with the BRAFV600E mutation." (PMID 32092958, 2020). "In patients with metastatic melanoma, identification of BRAF mutations in ctDNA has been associated with higher disease burden and worse prognosis and may precede clinical evidence of disease progression." (PMID 32010431, 2020). "In the case of metastatic melanoma, immunotherapy has a unique role due to the lower frequencies of BRAF mutation in choroidal melanomas and consecutive exclusion from treatment with specific BRAF tyrosine kinase inhibitors." (PMID 32685785, 2020). "In a previous study carried out on baseline detection of BRAF codon 600 mutations by Amplification-Refractory Mutation System (ARMS) qPCR in patients with metastatic melanoma harbouring a BRAF mutation in tumour tissue, we identified the mutation in 29 out of the 38 patients tested." (PMID 32664549, 2020). "This trial showed that ORR improved with fewer toxic effects with nivolumab against standard-of-care chemotherapy among patients with advanced, unresectable/metastatic melanoma who progressed following ipilimumab treatment, or a BRAF inhibitor if BRAF mutation positive (Category 1)." (PMID 32245016, 2020). "This suggests a potential synergistic effect for the use of immunotherapy in combination with EGFR-TKIs, according to the recent evidence of long-lasting antitumor responses of BRAF/MEK inhibitors with immunotherapy in the treatment of BRAF-mutated metastatic melanoma." (PMID 32760402, 2020). "In patients with unresectable advanced-stage metastatic melanoma, BRAF and NRAS mutations identified in ctDNA analysis at baseline and during treatment with targeted therapy against BRAF or immunotherapy have been associated with larger tumors, increased LDH levels, and brain metastases." (PMID 32010431, 2020). "Trametinib is used as an example, which is a kinase inhibitor indicated as a single agent for the treatment of BRAF-inhibitor treatment-naïve patients with unresectable or metastatic melanoma with BRAF V600E or V600K mutations as detected by an FDA-approved test." (PMID 33084582, 2020). "BRAF inhibitors (BRAFi) are standard of care for BRAF-mutated metastatic melanoma (MM)." (PMID 33081201, 2020). "Nivolumab became the second monoclonal antibody against PD-1 receptor to be approved by the FDA for the treatment of patients with unresectable or metastatic melanoma and disease progression following ipilimumab and a BRAF inhibitor (if BRAF V600 mutation-positive)." (PMID 32714859, 2020). "Additionally, the NCCN clinical practice guidelines recommend BRAF mutation testing in patients with resectable and unresectable or metastatic melanoma to guide treatment decisions (NCCN Clinical Practice Guidelines in Oncology3)?" (PMID 32695793, 2020). "Based on the mechanism of action of this tyrosine kinase inhibitor, the FDA drug label states that vemurafenib is only indicated for the treatment of patients with unresectable or metastatic melanoma with BRAF p.V600E mutation as detected by an FDA-approved test." (PMID 31427963, 2019).